APOE (apolipoprotein E)
Diseases named in the same sentence as APOE in open-access papers (continued):
Sharing a sentence is not in itself a finding about the gene and the disease.
hyperlipidemia (continued). "Hence, in this study, we investigated the effects of AEE on liver lipids through LC-MS-based untargeted lipidomics and the effects of AEE on gut microbiota based on cecal contents metagenomics by Illumina sequencing in HFD-induced hyperlipidemia ApoE−/− mice at the overall level." (PMID 36618709, 2022). "Thus, a comparison of the response to infection in SKO versus SKO/ApoE-null mice may permit a dissection of the effects driven by hyperglycaemia and hyperlipidemia." (PMID 33498782, 2021). "Therefore, apoE KO rabbits will serve as a new model for human hyperlipidemia." (PMID 33603774, 2021). "In addition, we observed an increased IL-12Rβ2, which account for mediating the immunosuppressive functions, in splenic Tregs and aortic Tregs in hyperlipidemia status; this suggests that IL-35 signaling is induced in splenic ApoE–/– Tregs and atherosclerotic aortas." (PMID 34622804, 2021). "Similarly, overexpression of ApoE resulted in a combined hyperlipidemia phenotype." (PMID 32155648, 2020). "Finally, we examined whether HtrA2 inhibits the development of plaque and Th17 differentiation in APOE knockout mice immunized with a proteoglycan to induce a hyperlipidemia-based animal model of RA." (PMID 28008946, 2016). "Approximately 75% of ApoE in blood is synthesized by the liver, followed by the brain, and this study confirmed by immunohistochemistry that ApoE is upregulated/expressed in many organs and tissues in the gerbil and is highly expressed in the brain and kidney of gerbils with hyperlipidemia." (PMID 25006576, 2014). "To further clarify whether the decreased cytokine production in ApoE−/− mice was due to long term hyperlipidemia or the disruption of ApoE gene expression itself, we further analyzed cytokine production in ApoE−/− and WT mice at the age of 6 wks in peritoneal infection model." (PMID 23977160, 2013). "Mixed hyperlipidaemia that could relate to an uncommon mutation in apoE in those of African descent was also not suspected." (PMID 22914997, 2012). "Because such attenuation is not seen in wild-type mice, in which the expression of Tlr2 and Tlr4 was further elevated after long-term infection compared with short-term infection, the deletion of the ApoE gene and/or the resulting hyperlipidemia may have affected the endothelial response." (PMID 21625524, 2011). "Pituitary removal combined with HFD induced hyperlipidemia, characterized by elevated serum total TC, TG, and LDL‐C levels, and reduced serum HDL‐C and IGF‐1 levels in ApoE−/−‐Hx mice." (PMID 41089172, 2025). "From the aspect of the molecular level, ApoA-1, ApoE, and lipoprotein lipase (LPL) genes are related to hyperlipidemia." (PMID 39598239, 2024). "TAO patients with hyperlipidemia exhibited higher TC, TG, LDL-c, apolipoprotein A (ApoA), apolipoprotein B (ApoB), and apolipoprotein E (ApoE) levels, as well as lower HDL-c levels, compared with TAO patients without hyperlipidemia (p < 0.05)." (PMID 39669501, 2024). "In particular, a significantly higher expression of MCP−1 and Vcam−1 was observed in ApoE–/– + WI + HFD mice compared to that in C57 + WI + HFD mice, indicating that combined mechanical injury and hyperlipidemia result in more pro-inflammatory changes." (PMID 36818346, 2023). "Apolipoprotein E knockout (ApoE−/−) mice with high increased total serum cholesterol levels demonstrated that obstructive MGD and hyperlipidemia were closely related by confirming MG dropout and disordered acini and ducts in the upper and lower eyelids." (PMID 35887773, 2022).
hyperlipidemia (continued). "Most such mouse models harbor a knockout in either the apolipoprotein E (ApoE) gene or the LDL gene, and both varieties develop hyperlipidemia and vascular inflammation when fed a cholesterol-enriched diet." (PMID 34293932, 2021). "To characterize hyperlipidemia-induced transcriptomic reprogramming in splenic Tregs of ApoE–/– mice, we performed RNA-Seq on splenic CD4+Foxp3+ Tregs of ApoE–/– mice and WT mice." (PMID 34622804, 2021). "In this study, we utilized the APOE*3-Leiden.CETP mouse, a well-established model for hyperlipidemia, characterized by increased plasma cholesterol and TG levels, that resembles lipoprotein metabolism of patients with familial dysbeta­lipoproteinemia (FD)." (PMID 31843957, 2020). "However, given the debatable role of hyperlipidaemia in aneurysm etiology and possible aggravation of aneurysm formation under Nrf2 transcriptional deficiency, we decided to use a model of AngII-induced AAA combined with fat-enriched diet in C57BL6/J mice, instead of the ApoE KO mice." (PMID 32617140, 2020). "Similarly, hyperlipidemia did not affect mdx-associated pathology in the diaphragm muscle: both mdx and mdx-ApoE mice on a Western diet showed significant levels of fibrosis and myofiber damage with similar decreases in healthy myofiber area at 4 and 7 months on Western diet." (PMID 28899419, 2017). "Because a high-energy diet impaires both glucose tolerance and insulin tolerance, we used the HFHS diet-fed ApoE−/− mice as a model for T2DM and hyperlipidemia." (PMID 28091547, 2017). "This single amino acid difference results in markedly reduced binding of APOE ε2 to the low density lipoprotein family of receptors, which in turn results in profound metabolic consequences, particularly Type III hyperlipidemia." (PMID 24782577, 2014). "To observe the effects of hyperlipidemia on intrarenal RAS activation and the specific location of RAS expression, we examined the protein expressions of intrarenal RAS components in ApoE KO mice by immunohistochemical staining and Western blot." (PMID 23570453, 2013). "In our study, macrophages from ApoE−/− mice showed inhibited transcription of TLR2, TREM-1, TREM-3, and CD14 in quiescent state, whereas only TREM-1 expression was influenced by hyperlipidemia in bacteria stimulated macrophages." (PMID 23977160, 2013). "Among these are rs2284017 (CACNG2) for lithium (as treatment for Bipolar Disorder), rs1801252 (ADRB1) for atenolol (Coronary Artery Disease), and rs429358 (APOC1, APOE) for ritonavir (HIV, HIV infections, Hyperlipidemias)." (PMID 23758991, 2013). "Plasma apoE protein concentrations have been reported to be higher in T2DM patients than in healthy controls, and plasma cholesterol ester transport protein (CETP) amounts are reportedly higher in hyperlipidemia individuals and considered atherogenic." (PMID 39234305, 2024). "For APOE, the drug AEM-28 is under study for hyperlipidemia." (PMID 38167548, 2024). "Also, the author reviews molecular pathways including the ApoA-1, ApoE, and LPL genes, which are related to hyperlipidemia, to explain the results." (PMID 39598239, 2024).
hyperlipidemia (continued). "We then examined apoE KO rabbits fed a cholesterol diet because apoE KO rabbits on a normal regular diet exhibited mild hyperlipidemia, which is not atherogenic." (PMID 35712258, 2022). "In the current study we investigated the response of elafibranor in APOE*3Leiden.CETP mice, a translational animal model that displays histopathological characteristics of NASH in the context of obesity, insulin resistance and hyperlipidemia." (PMID 33658534, 2021). "Considering the critical role of apoA-I and apoE in lipid metabolism, MT1-MMP may promote the development of hyperlipidemia by degrading apoA-I and apoE." (PMID 34297054, 2021). "We also examined the degree of hyperlipidemia in apoE−/− mice infused with Ang II with or without MRS2578." (PMID 32382533, 2020). "No betweensubgroup differences were found for BMI, hyperlipidaemia and number of ApoE ԑ4carriers (p > 0.05)." (PMID 30547694, 2020). "SNPs related to APOE and HLA showed stronger associations with non-OSA related phenotypes of hyperlipidemia, cholesterol, thyroid disease and/or celiac disease." (PMID 32711518, 2020). "Relevantly, a complete lack of the murine ApoE gene, i.e., ApoE-/- model, resulted in hyperlipidemia after feeding these mice a high-fat diet." (PMID 32046285, 2020). "The levels of Ang II in peripheral blood of ApoE−/− mice and C57 mice were comparable, indicating that the inhibitory effect of hyperlipidemia on ACEI was not mediated by Ang II." (PMID 32073735, 2020). "Whereas, Manabu Niimi and colleagues showed that homozygous (but not heterozygous) apoE KO rabbits showed mild hyperlipidemia, but when challenged with a cholesterol diet, exhibited greater diet-induced hyperlipidemia." (PMID 30885208, 2019). "Although no mutation was detected on the sgRNA 3-targeted locus of either founder, these founders exhibited hyperlipidemia and no apoE was detected in the plasma, suggesting that both founders were double KOs." (PMID 30885208, 2019). "Moreover, in APOE knock-out mice, endogenous apoC1 inhibited LPL, depending on its expression level, subsequently increasing VLDL and inducing hyperlipidemia." (PMID 31779116, 2019). "In vivo studies revealed that miR-26a overexpression attenuated hyperlipidemia by reducing the concentrations of TC, TG, LDL-C, and HDL-C, inhibited atherosclerotic lesion and inflammatory response in HFD-fed apoE−/− mice, suggesting the anti-arteriosclerotic effects of miR-26a in vivo." (PMID 29387339, 2018). "In normotensive ApoE-deficient mice, fed with Western-type diet, RDN attenuated atherosclerotic lesion formation at the aortic root without affecting hyperlipidemia." (PMID 27277003, 2016). "While a majority of the studies have been conducted in apoE-/- mice, this model is driven by hyperlipidemia and does not lend itself to investigation of several other aspects of the metabolic syndrome, namely DIO and insulin resistance." (PMID 25286043, 2014). "Wild type C57Bl/6 mice with normal ApoE expression do not have hyperlipidemia and have minimal plaque growth." (PMID 25354050, 2014). "Since serum cholesterol levels were not affected by rosuvastatin treatment, our finding is not due to the improvement of hyperlipidemia in ApoE−/− mice." (PMID 23509822, 2013). "ApoE−/− mice were not used because bone marrow cells expressing apoE will correct hyperlipidemia and essentially abolish atherogenesis." (PMID 24223214, 2013). "Therefore, we asked whether UCAO also induces infarction in mice after STZ-induced hyperglycemia and HFD-induced hyperlipidemia in 168 (92 C57BL/6 and 76 ApoE-/-) mice; 17 were excluded in each strain." (PMID 39744690, 2025).
hyperlipidemia (continued). "A recent advance in DMD modeling is the mdx-4CV mouse lacking apolipoprotein E (mdx-ApoE) with elevated levels of blood lipoprotein-associated cholesterol and triglycerides when on a Western diet (mdx-ApoEW), a key metabolic comorbidity of DMD, hyperlipidemia." (PMID 39716324, 2024). "ApoE-/- mice could form hyperlipidemia and other form plaques, regardless of whether they were fed a basic or high-fat diet." (PMID 36748219, 2023). "Feeding mice with a HFD for 16 weeks significantly increased the body weight and induced hyperlipidemia in ApoE−/−DCLK1f/f mice compared to the low‐fat diet (LFD) group, while macrophage‐specific DCLK1 deletion did not affect the increased body weight and serum lipid profile in HFD‐fed ApoE−/− mice." (PMID 36896602, 2023). "Studies with APOE2 mice did not shed additional light on whether impaired apoE-mediated lipoprotein clearance impacts obesity because these animals displayed hyperlipidemia even under basal dietary conditions." (PMID 36077289, 2022). "As such, it can be hypothesized that the null effect of SGC707 treatment on non-fasting plasma lipid levels in apoE knockout mice is related to a relatively minor contribution of hepatic VLDL production to the hyperlipidemia in this specific mouse model." (PMID 35013582, 2022). "This unexpected finding could, however, be explained by the fact that SGC707 treatment did not diminish the hyperlipidemia in Western-type diet-fed apoE knockout mice." (PMID 35013582, 2022). "We evaluated whether hyperlipidemia modulates Klotho expression in kidneys from C57BL/6 and hyperlipidemic apolipoprotein E knockout (ApoE KO) mice fed with a normal chow diet (ND) or a Western-type high cholesterol-fat diet (HC) for 5 to 10 weeks, respectively." (PMID 24386260, 2013). "In the present study, we tested our hypothesis that long term hyperlipidemia itself, rather than diet lipid, impaired the host immune response to periodontal infection in ApoE−/− mice compared to healthy C57BL/6 mice." (PMID 23977160, 2013). "Hence, diabetic ApoE−/− and ApoE−/−/TNFα−/− mice had both hyperglycemia and hyperlipidemia, whereas wt and TNFα−/− mice exhibited hyperglycemia but no significant changes in plasma lipids." (PMID 20856927, 2010). "Despite the effect of hyperlipidemia on skeletal muscle, the lack of dramatic exacerbation of cardiac muscle pathology in our mdx-ApoE model indicates that the DMD pathogenesis in these two muscle types may be different and not equally affected by increased circulating plasma lipids." (PMID 28899419, 2017). "Consistently with these reports, in the novel ApoE−/− rat model used herein, RDN reduced plasma aldosterone levels and attenuated aortic medial fibrosis formation, while hyperlipidemia and cardiac parameters were not affected." (PMID 27277003, 2016). "A diagnosis of hyperlipidemia and statin treatment did not affect plasma apoE levels (Mann–Whitney U-test, p = 0.922) even when accounting for race/ethnicity (B/AA: Mann–Whitney U-test, p = 0.928, NHW: Student’s t-test, p = 0.849), and APOE genotype." (PMID 37400888, 2023). "When non-diabetic mice of different genotypes were compared, ApoE−/− mice were found to express higher VCAM-1 levels than wt mice (p<0.05), suggesting that hyperlipidemia may induce VCAM-1 expression in retinal vessels." (PMID 20856927, 2010).
dyslipidemia (422 papers, 2005 to 2026). "It has been found through research that GPS ameliorates ApoE deficiency-induced dyslipidemia, while our prior research has established ApoE as indispensable for maintaining systemic iron homeostasis." (PMID 41527109, 2026). "Among the three major isoforms of ApoE (ε2, ε3, and ε4), the APOE4 allele has been most strongly associated with dyslipidemia due to its role in elevating plasma LDL cholesterol and impairing receptor-mediated lipoprotein clearance." (PMID 40572755, 2025). "Hypertension and dyslipidemia act synergistically with ApoE variants, increasing the risk of CAD, especially when combined with other risk factors such as smoking." (PMID 41465167, 2025). "This is in line with a higher risk of dyslipidemia in APOE-ε2 homozygous individuals in the presence of obesity." (PMID 40149441, 2025). "The additional predisposing factors for severe dyslipidemia in these patients appear to be the type of genetic variant (i.e., heterozygous vs. homozygous variants and location of the variant/residual APOE function), male gender and a post-splenectomy status." (PMID 40149441, 2025). "A population study illustrated that genetic variants at the APOE locus predict the development of metabolic syndrome." (PMID 40379890, 2025). "It is widely recognized that the Apolipoprotein E (ApoE) exhibits a significant association with dyslipidemia and atherosclerotic cardiovascular disease (ASCVD)." (PMID 40417124, 2025). "The relationship between obesity and neural vulnerability is modulated by the APOE genotype, which aligns with the findings that APOE4 carriers are at increased risk for metabolic syndrome and cardiovascular disease." (PMID 39347015, 2024). "In particular, the APOB XbaI (rs693) and the APOE ε4 variants were associated with diverse markers of dyslipidemia and CAD, while an independent role was observed for the LIPC T202T variant." (PMID 38638292, 2024). "This theory is supported by the abundant presence of lipids in drusen, polymorphisms of the apolipoprotein-E (APO-E) gene, and the involvement of dyslipidemia as a well-known risk factor in AMD." (PMID 39022525, 2024). "Preeclampsia (preE) is a severe multisystem hypertensive syndrome of pregnancy associated with ischemia/hypoxia, angiogenic imbalance, apolipoprotein E (ApoE)-mediated dyslipidemia, placental insufficiency, and inflammation at the maternal–fetal interface." (PMID 39857613, 2024). "The presence of ApoE mutation or deficiency has been shown in multiple population‐based studies to exacerbate dyslipidemia and hasten the progression of AS." (PMID 38628207, 2024). "Individuals with certain APOE alleles are more prone to both dyslipidemia (abnormal lipid metabolism) and kidney damage, underscoring the importance of considering genetic factors in clinical assessments." (PMID 39409014, 2024). "In the 1970s and 1980s, genetic research on APOE was mainly conducted from the viewpoint of dyslipidemia, and it was in the 1990s that it was reported that APOE genotypes confer major risk of AD." (PMID 35641666, 2023). "ApoE polymorphisms affect metabolic disorders, dyslipidemia, and T2DM via multiple processes (Alagarsamy, Jaeschke & Hui, 2022)." (PMID 37123009, 2023). "Dysfunctional ApoE can cause dyslipidemia and affect the metabolism of triglyceride-rich lipoproteins." (PMID 37372091, 2023). "Previous studies have shown that ApoE gene polymorphism is correlated with dyslipidemia and hyperuricemia." (PMID 36620636, 2022). "First, many previous studies have shown that APOE gene polymorphisms affect blood lipid metabolism, and dyslipidemia is a significant risk factor for the occurrence and development of atherosclerotic plaques." (PMID 36426228, 2022). "Our results argue for the screening of APOE variants in the dyslipidemia diagnosis, not only for the p.Leu167del but also for other rare variants throughout the APOE gene." (PMID 35628605, 2022).